BDNF (brain derived neurotrophic factor)
Diseases named in the same sentence as BDNF in open-access papers (continued):
Sharing a sentence is not in itself a finding about the gene and the disease.
mental disorder (124 papers, 2013 to 2025). A disease that has its basis in the disruption of mental process. "Our study aimed to evaluate the association of the interaction between 5HTTLPR and BDNF genetic polymorphisms with a profile of different mental disorders, using latent class analysis in a Chilean primary care population." (PMID 41438272, 2025). "Most studies in the literature are devoted to determining the frequency of the rs6265 polymorphism in the BDNF gene in mental disorders, while there are only a few studies regarding other polymorphisms of this gene and other neurotrophic factor genes." (PMID 40869303, 2025). "As a result, it can be thought that nutrition is related to neurogenesis and neuroplasticity underlying mental disorders through BDNF levels and possible dietary modifications will be important in treating mental disorders." (PMID 38329691, 2024). "Previous studies have indicated that BDNF in the brain is associated with the development of mental disorders." (PMID 39648800, 2024). "Several epigenetic modifications are potential mental disorder-related markers associated with air pollution, including DNAm levels of certain genes (such as BDNF), histone modification, and ncRNAs." (PMID 39058106, 2024). "The results of this study confirmed the association of rs6265 polymorphisms in the BDNF gene with mental disorders." (PMID 38397229, 2024). "BDNF is one of the most studied molecules in biological psychiatry, and its involvement in the stress response and associated mental disorders is widely recognized." (PMID 38796504, 2024). "As reduced BDNF is associated with several mental disorders, its role as a possible biomarker has been studied extensively." (PMID 35836661, 2022). "BDNF is the most studied gene, which is shown to be associated with many different mental disorders and is known to interact with various developmental pathways." (PMID 32171272, 2020). "Clarification of the underlying role of BDNF in the stress process will promote our understanding of the pathology of stress-linked mental disorders and provide a potent target for the future treatment of stress-related illness." (PMID 32085670, 2020). "BDNF is a neurochemical related to important brain processes such as neuroplasticity and neuronal survival, and it has been associated with several mental disorders." (PMID 30934558, 2019). "It was described in FEP that there were found associations between reduced BDNF gene expression levels in severe mental disorders, associated with increased inflammation and smaller hippocampal volume." (PMID 31849731, 2019). "In contrast, dysregulation of growth factors in the CNS has been associated with comorbid mental disorders, particularly BDNF and NGF." (PMID 29108028, 2017). "Although several studies have reported an association between mental disorders and serum levels of brain-derived neurotrophic factor (BDNF), this association is still poorly understood." (PMID 24593295, 2014). "This is the first study to show that the interplay between stress and sleep impacts BDNF levels, suggesting an important role of this relationship in the pathogenesis of stress-associated mental disorders." (PMID 24146812, 2013). "We assume that the interplay between decreased BDNF, chronic sleep impairment and increased stress levels is an essential mechanism in the pathogenesis of stress-associated mental disorders." (PMID 24146812, 2013). "Moreover, previous research has highlighted the crucial role of BDNF expression in various mental disorders, with increased BDNF levels being associated with symptom improvement." (PMID 40361833, 2025). "The brain-derived neurotrophic factor is associated with numerous mental disorders." (PMID 40806241, 2025). "However, there is a discrepancy in reported associations of methylation in the BDNF promoter with mental disorders, although most existing studies showed hypermethylation in the BDNF promoter in patients with mental disorders." (PMID 39058106, 2024).
mental disorder (continued). "Due to the complexity of the nervous system structure and species-specific peculiarities of intracellular signaling, the functional significance of the BDNF polymorphisms and their putative mechanisms underlying the predisposition to mental disorders are yet to be unveiled (Gören, 2016)." (PMID 38646100, 2024). "Previous research has implicated the involvement of BDNF in stress-related mental disorders." (PMID 36518560, 2022). "Moreover, as the BDNF protein in the brain has been implicated in the development of mental disorders, several research works have also proposed that peripheral BDNF can be considered as a potential marker of these diseases in humans." (PMID 32085670, 2020). "The Brain-derived neurotrophic factor (Bdnf) gene is involved in brain development, neuroplasticity, and synaptic transmission, and changes in its gene expression have been associated with numerous mental disorders." (PMID 33324186, 2020). "We were able to show that n-3 PUFAs intake is associated with serum BDNF levels in adolescents, corroborating to the suggestion that the relationship between mental disorders and BDNF may be mediated by the intake of nutrients such as n-3 PUFAs." (PMID 24593295, 2014). "The study of factors associated with both BDNF levels and mental disorders, such as n-3 polyunsaturated fatty acids (n-3 PUFAs), may help to elucidate the mechanisms mediating the relationship between the two variables." (PMID 24593295, 2014). "Our findings may help determine the nature of the association between mental disorders and serum levels of BDNF." (PMID 24593295, 2014). "Therefore, increased methylation levels in the BDNF promoter may serve as a potential indicator for air pollution-related risk of mental disorders." (PMID 39058106, 2024). "Although the correlation between BDNF gene polymorphism and cognitive function has been observed in persons with normal ageing, neurodegenerative diseases (e.g., AD and PD), multiple sclerosis, and some mental disorders, the evidence in patients with VaD (particularly SIVD) is limited." (PMID 37876876, 2023). "Elevated glucocorticoids reduce brain-derived neurotrophic factor (BDNF)-dependent upregulation of glutamate receptors by suppressing microRNA-132 expression, which is involved in various neural circuits and associated with the pathophysiology of mental disorders and neural diseases." (PMID 35911274, 2022). "However, from the evolutionary genetic point of view, mutations in the BDNF gene may still influence adaptions to environmental changes, especially for mental disorders." (PMID 26091093, 2015). "Therefore, the understanding of processes associated with both BDNF levels and mental disorders may ultimately help determine the underlying mechanisms responsible for the association between these two variables." (PMID 24593295, 2014). "BDNF also plays a physiological role in the pathogenesis and treatment of mental disorders through signaling pathways such as BDNF/TrkB, PI3K/PKB, and MAPK." (PMID 40513379, 2025). "Individuals with mental disorders often exhibit reduced expression of brain-derived neurotrophic factor (BDNF), which is essential for synaptic plasticity and neural signal transmission." (PMID 41153641, 2025). "For instance, previous studies have discovered a correlation between brain-derived neurotrophic factor (BDNF) methylation modification and different mental disorders." (PMID 39058106, 2024). "The decline of BDNF in the mPFC has been found in both clinical and preclinical studies in mental disorders related to estradiol fluctuations, such as premenstrual dysphoric disorder, PPD, and perimenopausal depression." (PMID 38743109, 2024). "BDNF also gives trophic support for many neurotransmitters known to impact mental disorders, and human and animal data implicate BDNF in the response to psychotropic medications." (PMID 38997217, 2024).
mental disorder (continued). "Anti-inflammatory action is linked to the regulation of TRP/KYN metabolism, enhancing 5-HT and BDNF levels, and thereby alleviating mental disorders." (PMID 38469409, 2024). "DNAm in the regulation of BDNF gene expression has been identified in cellular and animal models, as well as postmortem brain tissues and peripheral blood tissues of patients with mental disorders." (PMID 39058106, 2024). "Flavonoids are also reported to attenuate mental disorders involved in CREB/BDNF pathway, such as rutin, baicalin, and naringin." (PMID 37663268, 2023). "Patients suffering from several mental disorders exhibit reduced BDNF levels comparing to healthy population." (PMID 36672535, 2022). "BDNF, which plays an important role in maintaining brain functions, decreases as oxidative stress increases in cases of mental disorders." (PMID 36299904, 2022). "BDNF is crucial for the healthy development of the CNS, and its absence results in a multifaceted phenotype of cognitive and mental disorders, as evidenced from animal studies." (PMID 34734461, 2022). "BDNF can potentially be used as a biomarker of mental disorders or as a predictor of antidepressant efficacy." (PMID 33804468, 2021). "We demonstrated that Shati/Nat8l, a mental disorder-related gene, is upstream of BDNF in the dorsal striatum and upregulates striatal BDNF expression by promoting epigenetic modification." (PMID 34577589, 2021). "Brain-derived neurotrophic factor (BDNF), a critical member of the neurotrophic family, plays an important role in multiple stress-related mental disorders." (PMID 32085670, 2020). "In this review, we have summarized the effect of stress on BDNF and its relationship with various mental disorders." (PMID 32085670, 2020). "Largely due to the potent modulation of inflammation and neurogenesis, BDNF is closely involved in neuroplasticity and has long been proposed as a potential biomarker for many mental disorders." (PMID 31379619, 2019). "Then, pCREB transcribed the expression of the BDNF gene, upregulated the production of BDNF to benefit the hippocampal neurogenesis, and alleviated the mental disorders closely related to the hippocampus." (PMID 30984042, 2019). "In this review, we introduced the contribution of altered BDNF/TrkB system in the pathophysiology of brain diseases including mental disorders and neurodegenerative diseases." (PMID 30463271, 2018). "The role of VEGF and brain-derived neurotrophic factor (BDNF) in the pathogenesis of mental disorders was also studied." (PMID 29619128, 2018). "In general, the research findings are in agreement with putative involvement of BDNF in the pathogenesis of stress-related mental disorders." (PMID 28620285, 2017). "Given the emerging important role of BDNF in stress-related mental disorders, the aim of our investigation was to systematically summarize current evidence for altered BDNF signaling in experimental studies employing chronic social isolation of rats." (PMID 28620285, 2017). "A large number of studies showed that neurotrophic factors, especially BDNF plays an important role in mental disorders." (PMID 29552054, 2017). "With the help of CC1-EGFP, we provide a new way to study the functions of pre-synaptic TrkB in vivo, such as in brain development, LTP and BDNF-related mental disorders." (PMID 28749471, 2017). "And hub proteins, such as POMC, COMT, NPS, BDNF, also have the potential to be applied as targets for the diagnosis and treatment of mental disorders." (PMID 27917343, 2016). "Considering the close relationship between human BDNF and early life adversity, these findings have potential clinical implication for treating mental disorders." (PMID 26388728, 2015). "The epigenetic changes observed in the BDNF gene are considered causal in the pathogenesis rather than merely being an epiphenomenon of mental disorders." (PMID 39058106, 2024).
mental disorder (continued). "BDNF has also been linked to a number of personality traits, as evidenced by studies conducted on healthy individuals without mental disorders." (PMID 39224579, 2024). "Combined with recent studies, BDNF plays an important role in the cardiovascular system, so influencing BDNF through exercise to exert multiple biological effects can help to ameliorate physical and mental disorders in patients." (PMID 38707889, 2024). "BDNF is a biomarker of enduring interest to researchers working on mental disorders." (PMID 37891727, 2023). "BDNF plays a vital role in mental disorders and neurogenesis." (PMID 38273824, 2023). "CREB is a known regulator of BDNF signal transduction, and BDNF has repeatedly been suggested as a candidate gene for CT and as a marker of active severe mental disorder regardless of the diagnostic entity." (PMID 35501310, 2022). "Furthermore, it also suggests that BDNF alteration in general mental disorder reflect response to general stress and mental illness, independent of presented symptoms." (PMID 35114967, 2022). "Early-life stress may also impact methylation of other genes related to the pathophysiology of various mental disorders, such as BDNF, COMT, MAOA, FKBP5, and SLC6A4." (PMID 33284958, 2021). "The neurotrophin hypothesis for BDNF is formed based on the fact that any stress‐related mental disorders such as sleep disturbances result from stress‐induced decreases in BDNF expression." (PMID 34807519, 2021). "According to the neurotrophin hypothesis of depression, BDNF and its receptor, TrkB, serve as important mediators in mental disorders, such as depression." (PMID 34439529, 2021). "BDNF has been shown to be involved in various brain pathologies and mental disorders." (PMID 32916851, 2020). "Notably, the strategy of combined measures of tPA‐BDNF pathway proteins in serum (including pro‐BDNF) has been recently adopted in subjects affected by different mental disorders." (PMID 30403004, 2019). "Together, our results suggest that adolescent isolation may result in mental disorders during adulthood and that this may stem from an inability to forget the unpleasant memories via BDNF-mediated synaptic plasticity." (PMID 25860250, 2015). "Nevertheless, evidence does suggest that serum BDNF levels may reflect what occurs in the brain since in recent years, the involvement of BDNF in the pathogenesis of several mental disorders has been corroborated by a series of biochemical studies." (PMID 24024214, 2013). "Besides that, the relationship between central and peripheral BDNF levels remains unclear, with studies offering both supporting and opposing evidence regarding the use of peripheral BDNF as a reliable biomarker for mental disorders." (PMID 40264519, 2025). "This disposable salivary BDNF detection technology may beextended to multiplexed assays or integrated into multianalyte salivarystrips for applications in personalized medicine and wellness, includingearly monitoring of health status and mental disorders." (PMID 40821874, 2025). "Thus, the mechanism through which Rg3 enhances cardiac function while ameliorating mental disorders may involve modulating inflammation, catecholamine, the BDNF system, the HPA axis, and oxidative stress." (PMID 38469409, 2024). "Mental disorders are linked to dysfunctions in the sympathetic-adrenomedullary system (SAM), and the hypothalamic-pituitary-adrenal (HPA) axis, as well as to inflammation, oxidative stress, and impairments in the brain-derived neurotrophic factor (BDNF) system." (PMID 38469409, 2024). "Consequently, peripheral and central BDNF are related, and mental disorders may be replicated by serum BDNF." (PMID 38752280, 2024). "In addition, in some mental disorders where cognition is affected, BDNF is low." (PMID 38398813, 2024).
mental disorder (continued). "Impairments in BDNF expression and maturation may inflict the manifestation of cognitive and mental disorders at different levels: via the dysfunction of the brain dopaminergic system caused by dopaminergic neuron death, or via alterations in the plasticity/stability of inter-neuron networks." (PMID 38646100, 2024). "The central BDNF correlation with peripheral BDNF concentrations remains unclear, with evidence both in favour and against the potential viability of peripheral BDNF as a candidate biomarker for mental disorders." (PMID 39063164, 2024). "Nevertheless, as BDNF is associated with several mental disorders, MAPK3 differential expression may also not be restricted to social anxiety." (PMID 37181876, 2023). "BDNF acts as a vital trophic protein for neuronal survival, and also modulates cholinergic neuron activity, which is critical for cognition and may impact on mental disorders." (PMID 33804682, 2021). "This relationship may also provide an explanation for decreased BDNF levels in subjects complaining of perceived stress and levels in patients with stress-related mental disorders, because sleep is commonly disturbed both in stressful conditions and most mental disorders." (PMID 29944703, 2018). "Furthermore, it was found that hub proteins, such as COMT, POMC, NPS and BDNF, might be the potential targets for mental disorders therapy." (PMID 27917343, 2016). "BDNF and NGF both are essential proteins for neuron's growth, and their dysregulation is seen in various mental disorders." (PMID 38376038, 2024). "Brain-derived neurotrophic factor (BDNF), serotonin transporter (SLC6A4), and oxytocin receptor alteration (OXTR) affect major brain systems with a possible expression of related mental disorders." (PMID 35409300, 2022). "The research progress of NR3C1, FKBP5, BDNF, KITLG and other genes will provide a solid theoretical basis for the improvement of mental disorders in children after trauma." (PMID 36458128, 2022). "The findings in the present study indicated that each serum level of tPA, PAI-1, BDNF, proBDNF, TrkB and p75NTR in tPA-BDNF pathway might yield a relatively high level of diagnostic power, but they failed to play a role in differentiation of mental disorders." (PMID 28761093, 2017). "Significant associations between rs6265 BDNF and rs1800955 DRD4 and mental impairments were detected when comparing the general group of patients with mental disorders (without separation into diagnoses) to the control group." (PMID 38397229, 2024). "There was a lack of correlation between the severity of the mental disorder and serum BDNF concentration." (PMID 37509026, 2023). "Alteration in the level of BDNF in the CNS is involved in the pathophysiology of numerous brain diseases such as Parkinson’s disease, Alzheimer's disease, cerebrovascular accident (CVA), and mental disorders." (PMID 35911274, 2022). "It is fair to conclude that alterations in BDNF levels are neither disease nor treatment specific since stress is a major factor in mental disorders." (PMID 35836661, 2022). "Our results provide further evidence for a role for BDNF in the pathophysiology of mental disorders, especially revealed in the group of patients not using psychotropic medication." (PMID 35114967, 2022). "Our study suggests that traumatic stress in adolescence leads to immediate and long-term mental disorders, neuronal morphological changes, lower BDNF level and increased H3K9me2 level in the HIP and PFC, indicating that H3K9me2/BDNF dysfunction plays a key role in pathogenesis of PTSD." (PMID 32850808, 2020). "Based on this evidence, it has been suggested that SorCS2 could be a possible link between proBDNF/BDNF signaling, synaptic plasticity (LTD/LTP) and mental disorders." (PMID 31024262, 2019).